G6PD (glucose-6-phosphate dehydrogenase)
Diseases named in the same sentence as G6PD in open-access papers (continued):
Sharing a sentence is not in itself a finding about the gene and the disease.
haemolytic anaemia (continued). "The only available anti-malarial agents against latent malaria, the 8-aminoquinolines (primaquine and tafenoquine) cause potentially serious haemolytic anaemia in glucose-6-phosphate-dehydrogenase deficient (G6PDd) patients, and hence, very often imposes a critical barrier to safe access." (PMID 36872344, 2023). "We found a total of 41 cases of haemolytic anaemia episodes associated with NF reported in the scientific literature, including 17 case reports, of which 24 and 4 were in confirmed and highly probable G6PD-deficient patients, respectively." (PMID 35529053, 2022). "The cyanosis following pamaquine therapy was caused by methaemoglobinaemia, and the sporadic severe haemolytic anaemia was later identified as resulting from the oxidant drug susceptibility of erythrocytes with reduced glucose-6-phosphate dehydrogenase (G6PD) activity." (PMID 34997616, 2022). "However, tafenoquine requires a diagnosis of the G6PD status of each individual, since it can cause acute haemolytic anaemia as seen in a study in the western coastal region of Southwest Sumba." (PMID 34174880, 2021). "Moreover, infection is thought to be another common cause of haemolytic anaemia in G6PD-deficient individuals." (PMID 31089417, 2019). "However, primaquine can also induce oxidative stress causing a spectrum of haemolytic anaemia ranging from mild to severe haemolysis in G6PD-deficient individuals." (PMID 31590661, 2019). "However, primaquine and tafenoquine can cause acute haemolytic anaemia in individuals with low G6PD enzyme level." (PMID 31590661, 2019). "Exposure of G6PD-deficient individuals to oxidative stress, such as consumption of fava beans, use of certain drugs, and maybe infections, can lead to haemolytic anaemia." (PMID 31089417, 2019). "However, this drug induces haemolytic anaemia among glucose-6-phosphate dehydrogenase (G6PD) deficient individuals." (PMID 30819192, 2019). "However, PQ causes haemolytic anaemia in moderate to severely glucose-6-phosphate dehydrogenase (G6PD)-deficient individuals." (PMID 29615050, 2018). "Additionally, there are limited data on the safety of primaquine, given its known association with haemolytic anaemia in patients who are deficient in glucose-6-phosphate dehydrogenase (G6PD)." (PMID 28693488, 2017). "The data indicates that ~1/23 males from the Alto do Juruá could be G6PD deficient and at risk of haemolytic anaemia if treated with primaquine." (PMID 28619120, 2017). "Infected individuals are treated with primaquine, which can induce haemolytic anaemia in glucose-6-phosphate dehydrogenase (G6PD)-deficient individuals and may lead to severe and fatal complications." (PMID 28619120, 2017). "At the same time, under-dosing of primaquine may provide false reassurance as to the incidence and severity of major drug-related adverse effects such as haemolytic anaemia in G6PD deficient patients, and methaemoglobinaemia." (PMID 24828338, 2014). "Importantly, both the WST8 test, and the R&D test enabled identification of individuals with low G6PD enzyme activity with the highest risk for haemolytic anaemia (<30% activity)." (PMID 23782846, 2013). "Chlorproguanil-dapsone-artesunate (CDA) was a promising artemisinin-based combination therapy (ACT), but its development was prematurely stopped because of safety concerns secondary to its associated risk of haemolytic anaemia in glucose-6-phosphate dehydrogenase (G6PD)-deficient individuals." (PMID 22546009, 2012). "However, in G6PD-deficient individuals, haemolytic anaemia occurred more frequently in children treated with CDA (5/9) than in those treated with other ACT though the difference was not significant (p = 0.49)." (PMID 22546009, 2012).
haemolytic anaemia (continued). "Glucose-6-phosphate dehydrogenase deficiency poses a significant impediment to primaquine use for the elimination of liver stage infection with Plasmodium vivax and for gametocyte clearance, because of the risk of life-threatening haemolytic anaemia that can occur in G6PD deficient patients." (PMID 20684792, 2010). "However, the occurrence of haemolytic anaemia leading to death in a G6PD deficient patient highlights the importance of monitoring for rare, but serious adverse events." (PMID 19948038, 2009). "Of the nine patients with pre-treatment haemoglobin concentrations below 7 g/dL who were treated with tafenoquine, one returned on day 5 with acute haemolytic anaemia symptoms (G6PD normal)." (PMID 38365417, 2024). "Of six patients with pre-treatment haemoglobin concentrations <7 g/dL treated with daily primaquine, one returned on day 5 with symptoms of acute haemolytic anaemia (G6PD normal)." (PMID 38365417, 2024). "The enzyme G6PD protects against the oxidative stress of haemolytic anaemia induced by both infection and anti-malarials." (PMID 38062464, 2023). "A recent report has indicated that patients with G6PD MahidolG487A presented symptoms of acute haemolytic anaemia after taking an incorrect dose of PQ." (PMID 36038921, 2022). "Since PQ can induce haemolytic anaemia in G6PD–d persons, testing for G6PD status especially in children, must be performed prior to PQ treatment." (PMID 36460990, 2022). "These populations also demonstrate high levels of deficiency in the enzyme glucose-6-phosphate dehydrogenase (G6PD), and both G6PD deficiency and fava beans increase risk of “favism,” a form of acute haemolytic anaemia." (PMID 32508752, 2020). "Deficient G6PD activity is well examined in red blood cells (RBC), as it often results in clinical manifestation of mild to severe haemolytic anaemia following exposure to various oxidative agents such as certain drugs." (PMID 30424472, 2018). "While prescribing primaquine for 14 days to females who are considered to have intermediate G6PD activity, counselling on potential development of signs and symptoms of haemolytic anaemia is required." (PMID 28535765, 2017). "Widespread G6PD testing would be necessary to prevent adverse reactions like haemolytic anaemia, making it important to assess whether health systems in this region are prepared to support such testing." (PMID 40990168, 2025). "Like primaquine, tafenoquine can produce acute haemolytic anaemia in G6PD-deficient patients, but unlike primaquine, once started it cannot be discontinued." (PMID 39070600, 2024). "The TRuST study concluded that quantitative G6PD testing followed by P vivax radical cure was highly feasible in the Brazilian Amazon with no concerning risk for acute haemolytic anaemia." (PMID 38452779, 2024). "However, they are at risk of acute haemolytic anaemia upon exposure to oxidant agents such as antimalarial medicines primaquine and tafenoquine, for which WHO recommends G6PD testing before use." (PMID 39070600, 2024). "Overall, five G6PD-deficient and 11 G6PD-intermediate patients received tafenoquine, with one reporting symptoms of acute haemolytic anaemia at day 5, which was not considered to be drug related." (PMID 38365417, 2024). "Of the 12 patients with acute haemolytic anaemia treated with primaquine, drug-related acute haemolytic anaemia was suspected for seven (58·3%), including one G6PD-intermediate patient (onset day 3, haemoglobin 6·8 g/dL) and six G6PD-deficient patients (onset days 3–6, haemoglobin 4·3–8·1 g/dL)." (PMID 38365417, 2024). "VigiBase, the WHO global database of individual case safety reports (ICSRs) that currently includes almost 23 million reports, was contacted enquiring about cases related to NF intake that included G6PD, haemolytic anaemia, haemolysis and methaemoglobinaemia cases." (PMID 35529053, 2022).
haemolytic anaemia (continued). "Four weeks of supplementation with α-lipoic acid, a sulphur-containing compound and potent antioxidant, has shown to improve some indices of redox status in G6PD-deficient individuals with no signs of haemolytic anaemia." (PMID 31089417, 2019). "One article from Thailand reported that highly active antiretroviral therapy did not cause haemolytic anaemia nor did it cause hyperbilirubinaemia in G6PD-deficient patients living with HIV." (PMID 29082022, 2017). "A case of Dapsone induced haemolytic anaemia was reported from the Teaching Hospital, Anuradhapura, in a boy treated for leprosy and having normal G6PD activity, while a case of nitrofurantoin induced haemolysis was recently reported in a G6PD deficient pregnant woman." (PMID 28152025, 2017). "In Curaçao, one case of haemolytic anaemia in a G6PD-deficient subject was related to a febrile non-defined viral infection." (PMID 24568147, 2014). "All haemolytic anaemia cases reported from the literature and databases, including subsets of G6PD confirmed and highly probable cases, were added regardless of whether they were due to an overdose, maternal drug exposure or possible roles of suspect or concomitant drugs." (PMID 35529053, 2022). "The results from this study indicate that moderate intensity exercise at approximately 75% MHR may not cause oxidative stress or haemolytic anaemia in G6PD-deficient individuals." (PMID 31089417, 2019). "Since G6PD deficient individuals have lower endogenous antioxidant system, intense exercise could result in increased oxidative stress in RBC and myocytes, which in turn could cause haemolytic anaemia and/or muscular symptoms, respectively." (PMID 30424472, 2018). "However, this study showed no signs of haemolytic anaemia in other G6PD and PKLRR41Q mutations." (PMID 36038921, 2022). "Six (three in the 0.25 mg/kg primaquine arm including two G6PD-deficient patients and three in the no primaquine arm) came from one study meeting a predefined SAE criterion of acute haemolytic anaemia." (PMID 36109733, 2022). "In multicentre clinical trials in G6PD-normal patients, chloroquine plus tafenoquine reduced the 6-month incidence of P vivax malaria recurrence by 70% (95% CI 60–78) compared with chloroquine plus placebo, with no occurrences of drug-induced acute haemolytic anaemia." (PMID 38365417, 2024). "Furthermore, since RBC are extremely active during intense exercise, G6PD-deficient RBC might not be able to withstand the exercise-induced oxidative stress, and acute haemolytic anaemia could develop." (PMID 31089417, 2019). "Where G6PD testing is not available, WHO recommends “all females should be considered as potentially having intermediate G6PD activity and given the 14-day regimen of primaquine, with counselling on how to recognise symptoms and signs of haemolytic anaemia”8." (PMID 32766454, 2020).
hepatocellular carcinoma (64 papers, 2013 to 2026). A malignant tumor that arises from hepatocytes. "In liver cancer, elevated G6PD expression is significantly associated with metastasis and poor prognosis of hepatocellular carcinoma (HCC) in patients." (PMID 39859324, 2025). "An independent risk factor associated with the development of hepatocellular carcinoma (HCC) has been identified as glucose-6-phosphate dehydrogenase (G6PD)." (PMID 39315094, 2024). "Specifically, this study establishes a connection between miR-122 and G6PD levels in hepatitis B virus-associated hepatocellular carcinoma, suggesting its clinical relevance." (PMID 37627157, 2023). "The findings are to a some extent in agreement with the recent findings on the metabolic changes associated with enhanced glucolysis in G6PD-deficient hepatoma cells and human G6PD-deficient RBCs in response to diamide." (PMID 26981882, 2016). "The glycolysis pathway is also enhanced in G6PD-deficient hepatoma cells under diamide-induced oxidative stress." (PMID 26981882, 2016). "Consequently, we investigated the tumor mutation burden of G6PD, and its prognostic impact on hepatocellular carcinoma and evaluated the plausibility of the impact." (PMID 38297250, 2024). "Indeed, most of PQ-TZs tested were significantly less toxic than PQ against human hepatoma and monkey kidney cells in vitro, as well as to normal and G6PD deficient human erythrocytes." (PMID 28279180, 2017). "These compelling results imply a potential association between G6PD and hepatocellular carcinoma cell proliferation, as well as an unfavorable prognosis in patients afflicted with HCC." (PMID 37601657, 2023). "In hepatocellular carcinoma, G6PD inhibits ferroptosis by targeting cytochrome P450 reductase, promoting cell growth, metastasis, and tumorigenesis." (PMID 40165005, 2025). "Reports suggested that G6PD OE in hepatocellular carcinoma or ccRCC was mediated by Nrf2 or through synergistic overactivation of the NF-κB and pSTAT3 signaling pathways, respectively." (PMID 39894218, 2025). "In the end, miR-206 directly targets glucose-6-phosphate dehydrogenase (G6PD) and downregulates the expression of G6PD to inhibit hepatocellular carcinoma cell growth." (PMID 37032500, 2024). "FZD1 and G6PD are two DR genes that serve as biomarkers for predicting the prognosis of patients with hepatocellular carcinoma." (PMID 38507875, 2024). "These genes, FZD1 and G6PD, demonstrate protumoral functions in hepatocellular carcinoma via various mechanisms." (PMID 38507875, 2024). "The potential diagnostic utility of G6PD and Decision Tree C5.0 for LIHC opens up a novel avenue for early detection and improved treatment strategies for hepatocellular carcinoma." (PMID 38297250, 2024). "As previously reported, ID1 induces c-Myc activation through the Wnt/β-catenin pathway, thereby promoting G6PD transcription, and then activating the pentose phosphate pathway, resulting in chemoresistance to oxaliplatin in hepatocellular carcinoma." (PMID 39052126, 2024). "The SNHG1-miR-199a-FANCD2/G6PD axis inhibits ferroptosis in hepatocellular carcinoma, serving as a potential marker for prognosis and therapy." (PMID 39315094, 2024). "GO, KEGG and GSEA analysis was executed to probe the possible involvement of G6PD in hepatocellular carcinoma formation." (PMID 38297250, 2024). "Existing evidence has shown that the level of G6PD is increased in a range of tumor cells, such as urinary tract cancer, breast cancer, cervical cancer, hepatocellular carcinoma, bladder cancer, lung cancer, and ovarian cancer." (PMID 37601657, 2023).
hepatocellular carcinoma (continued). "Previous studies have indicated that G6PD overexpression was associated with a poor prognosis in certain types of cancer, including AML, hepatocellular carcinoma, invasive breast carcinoma, and mesothelioma." (PMID 38098504, 2023). "It was shown that G6PD is activated by TSP50 along with the development of hepatocellular carcinoma." (PMID 36860325, 2023). "Bcl-2 associated athanogene 3 (BAG3) directly interacts with G6PD and consequently inhibits its dimerization and activity, leading to suppression of the PPP flux and the proliferation of hepatocellular carcinomas (HCCs)." (PMID 35207558, 2022). "The observed G6PD overexpression observed is in conformity with previous reports, that established the correlation between the gene overexpression and the G6PD protein level in human hepatoma cells under H2O2 exposure." (PMID 34679753, 2021). "In contrast to other studies, we found that the effect of TSP50 on cell proliferation is mediated by the inhibition of the acetylation of the G6PD K171 site in hepatoma cell lines, which is novel finding of this study." (PMID 33630390, 2021). "Here we established that the activities of the metabolic enzyme G6PD are regulated by TSP50 in hepatoma cell lines." (PMID 33630390, 2021). "Ectopic expression of miR-122 decreases G6PD expression in hepatocellular carcinoma cells and HepG2 cells." (PMID 31500396, 2019). "To analyze the expression profile of G6PD in liver cancer, we queried Liver and Hepatocellular Cancer (LIHC) RNA-seq data from The Cancer Genome Atlas (TCGA) database using the Xena Cancer Browser (xena.ucsc.edu; xenabrowser.net)." (PMID 29904144, 2018). "In search of evidence that HBV infection stimulates G6PD expression, we checked G6PD protein in human hepatoma Huh7 cells expressing HBV genomic DNA, and HepG2.2.15 cell, a HBV-replicating cell line." (PMID 26583321, 2015). "The toxicity of this prodrug was evaluated in in vitro assays using a human hepatoma cell line (HepG2), a monkey kidney cell line (BGM), and human red blood cells deficient in the enzyme glucose-6-phosphate-dehydrogenase (G6PD)." (PMID 25133630, 2014). "Kim et. al (2008) revealed that the activity of malate dehydrogenase is antagonized by the activity of glucose 6-phosphate dehydrogenase in the dehydroepiandrosterone (DHEA) treated hepatocellular carcinoma rats." (PMID 23874655, 2013). "Furthermore, we observed that G6PD knockdown in hepatocellular carcinoma cells led to reduced proliferation, migration, and invasion abilities." (PMID 38297250, 2024). "Another study demonstrated that the ID1/Wnt/β-catenin signaling cascade regulates the attachment of c-Myc with the G6PD promoter and increases the transcription of G6PD, resulting in enhanced cell proliferation and drug resistance for oxaliplatin in hepatocellular carcinoma (HCC)." (PMID 38139067, 2023). "Furthermore, we also performed clinical validation and in vitro experiments to further validate the role of G6PD in hepatocellular carcinoma (HCC) cells and its correlation with prognosis." (PMID 37601657, 2023). "Next, a literature search was conducted to focus on proteins specifically associated with liver disease in general, which selected 20 proteins, seven of which (i.e., CEP55, CLIC1, EPS15L1, G6PD, KIF11, SLC1A5, and TK1) were found to be specifically associated with hepatocellular carcinoma." (PMID 37627157, 2023). "Among these, a negative correlation was observed between miR-122 and glucose-6-phosphate dehydrogenase levels in the livers of patients with hepatitis B virus-associated hepatocellular carcinoma." (PMID 37627157, 2023). "It has been reported that Nrf2 could contribute to elevated G6PD expression in hepatocellular carcinoma through the transcriptional regulatory effect." (PMID 33041664, 2020). "An investigation on hepatocellular carcinoma indicated that G6PD could activate the STAT3 pathway to promote EMT and further favor cancer metastasis." (PMID 32028979, 2020).